IL22 (interleukin 22)
Diseases named in the same sentence as IL22 in open-access papers (continued):
Sharing a sentence is not in itself a finding about the gene and the disease.
colitis (continued). "In another murine study on a model of anti-CD40 colitis, THC was also able to reduce the circulating levels of TNF-α, interleukin 17A (IL-17A), interleukin 22 (IL-22), and interferon-γ (IFN-γ), leading to a significant reduction in both systemic and local inflammation." (PMID 36289755, 2022). "In colitis models, oral uptake of these particles decreased the pro-inflammatory cytokines (TNF-α, IL-6, and IL-1), raised the anti-inflammatory cytokines (IL-10 and IL-22), and was shown to be a preventive therapy against colitis-related malignancy." (PMID 36298592, 2022). "Moreover, butyrate supplementation in mice promotes IL-22 expression by CD4+ T cells and innate lymphoid cells (ILCs) and partially protects wild-type (WT) mice from C. rodentium-induced colitis." (PMID 34362137, 2021). "While the wild type mice survived DSS-induced colitis, MSC-/- mice showed increased production of pro-inflammatory cytokines (e.g., IL-22, IL-6, TNF-α) in the gut, with more infiltrating immune cells in colon tissues, reduced body weight, and earlier onset of death." (PMID 34992594, 2021). "After colitis induction, the KD protected intestinal barrier function, and reduced the production of RORγt+CD3− group 3 innate lymphoid cells (ILC3s) and related inflammatory cytokines (IL-17α, IL-18, IL-22, Ccl4)." (PMID 33888680, 2021). "Conversely, IL-22−/− mice infected with C. rodentium experience more severe colitis than WT mice and show no benefit from butyrate supplementation, thus suggesting a crucial role for IL-22 as a critical mediator acting downstream butyrate signaling pathway." (PMID 34362137, 2021). "The cytokine production profile in mesenteric lymph nodes (MLN) indicated that secretion of the inflammatory cytokine (IL-22) and anti-inflammatory/regulatory cytokine (IL-10) was significantly upregulated and downregulated, respectively, in DSS colitis mice compared with control mice." (PMID 34681392, 2021). "The small RNAs contained in ginger ELNs had protective effects against DSS-induced colitis by reducing the levels of pro-inflammatory cytokines, such as IL-1β and TNF-α, and by promoting the expression of interleukin 22 (IL-22) through I3A, which activates the aryl hydrocarbon receptor pathway." (PMID 34065193, 2021). "Thus, although IL-22 maintains gut barrier integrity by stimulating the production of mucin, antimicrobial peptides, and tight junction proteins in healthy gut, during colitis it is overproduced especially in HSD-fed mice and could contribute to greater damage of the mucosa." (PMID 33339337, 2020). "IL23 is the key cytokine responsible for triggering IL22 production; therefore, we tested the hypothesis that IL23 blockade would resolve colonic epithelial ER stress in human colitis." (PMID 31792136, 2020). "The observation that mice lacking IL-22 induction ability are more prone to develop colitis, illustrates the central role for IL-22 in regulating the development of colitis." (PMID 32957545, 2020). "In mice, the absence of Nkx2-3 proved to be protective in DSS-induced colitis through an IL-22-independent mechanism." (PMID 32859051, 2020). "IL-21 also promotes IL-22 expression in mucosal T-cells through a mechanism involving STAT3, retinoid-related orphan receptor γt, and aryl hydrocarbon receptor, thereby helping protect immunodeficient mice from DSS colitis." (PMID 32855621, 2020). "IL-22 acts on epithelial cells to mediate their barricade to maintain antimicrobial defense mechanisms in the host by reducing Alcaligenes spp., segmented filamentous bacteria (SFB) in the gut, and declining TH17 cell-mediated colitis." (PMID 33316984, 2020). "Administration of some strains of L.reuteri alone or in combination with other Lactobacillus strains has been reported to prevent DSS-induced colitis in mice due to various mechanisms and some studies suggest that AHR activation and enhanced IL-22 production play a critical role in the process." (PMID 33193381, 2020).
colitis (continued). "Whereas in antibody treatment experiments, blockade of TL1A or DR3 started after onset of DSS-induced colitis, before which no possibly impaired epithelial integrity due to lack of IL-22 occurred." (PMID 31358760, 2019). "In addition, RA resulted in the reduction of the inflammatory-related cytokines, such as IL-6, IL-1β, and IL-22, and protein levels of COX-2 and iNOS in mice with DSS-induced colitis." (PMID 28383063, 2017). "Most recently, the protective effects of H. diminuta infection, and of the myeloid population induced by the parasite, have been shown to be inhibited by IL-22, but promoted by IL-25, with disease scores in DNBS-induced colitis exacerbated by anti-IL-25 antibody treatment." (PMID 28302598, 2017). "Consequently, the Ahr-IL-22 axis provides resistance to the fungus Candida albicans and protection from dextran sulfate sodium (DSS)-induced colitis." (PMID 29354125, 2017). "As IL-22 was induced in ILC3 by IL-23 signalling, these data suggest that IFN-γ may contribute to IL-23-IL-23R-dependent colitis." (PMID 27578924, 2016). "In addition, interaction of surface LT on ILC3s with LTβR on intestinal epithelial cells can lead to IL-22 production in colon in C. rodentium and DSS-induced colitis models." (PMID 27578924, 2016). "For example, mice lacking Muc2 and secreted mucus develop colitis but no pathology in the ileum due to the lower abundance of bacteria in the small intestine and induction of the IL-22 pathway of genes regulating barrier function and innate defences." (PMID 26843130, 2016). "In the presence of T-bet, IL-23-driven colitis is multifunctional in nature and not functionally dependent on either IL-17A or IL-22." (PMID 27193261, 2016). "As IL-17 and IL-22 are major downstream effectors of the IL-23 signalling axis we first investigated their role in anti-CD40 colitis." (PMID 26780670, 2016). "Moreover, rIL-22 treatment of colonic epithelial cells isolated from mice with DSS-induced colitis induced activation of STAT3 signaling pathway that regulates gut homeostasis and was shown to promote wound healing in an IL-22-dependent manner." (PMID 26199463, 2015). "IL-22-producing ILC are important regulators of intestinal homeostasis, they are generated in an IL-7/IL-7R-dependent fashion and protect Rag− mice from DSS-induced colitis." (PMID 22384106, 2012). "Moreover, treatment of mice with an AhR antagonist reduced IL-22 production and enhanced the severity of TNBS-colitis." (PMID 22082127, 2011). "Like IL-17A knockout mice, mice lacking IL-22 develop severe colitis following oral DSS administration as compared to wild-type mice." (PMID 22082127, 2011). "IL-23 appears to protect against early C. rodentium mortality via Th17 cell secretion of IL-22 rather than IL-17, which peaks during maximal colitis at 2 WPI." (PMID 20976045, 2010). "In a T-cell-driven adoptive transfer (AdTr) colitis mouse model, liraglutide significantly improved disease activity markers, including histological activity in colonic tissue and the colon weight-to-length ratio, likely due to its ability to reduce CCL20, IL-33, and IL-22." (PMID 40426955, 2025). "However, our current study, adding to our previous report, suggests that while IL-22 production increases in response to colitis induction, AhR does not appear to regulate this cytokine to promote any protective effects." (PMID 39229279, 2024). "Interestingly, previously observed protective IL-22 production derived from immune cells was maintained in AhRΔIEC mice despite no longer showing protection against colitis after treatment with I3C." (PMID 38397081, 2024). "In addition, while IL-22 production by Th22 is affected by colitis induction, this process appears to be independent of AhR, at least in response to an AhR ligand like I3C." (PMID 39229279, 2024).
colitis (continued). "However, our current report seems to suggest that the majority of IL-22 during colitis, and especially during I3C treatment, does not come from neutrophils, but instead other lymphocyte populations." (PMID 39229279, 2024). "Notably, treatment with an anti-IL-22 antibody has been demonstrated to suppress myofibroblast proliferation and subsequent fibrotic symptoms, a common complication of CD, in a trinitrobenzene sulfonic acid (TNBS)-induced colitis model." (PMID 39379604, 2024). "To gain a deeper understanding of the mechanism by which TP2 alleviates colitis, we utilized ELISA technology to assess typical pro-inflammatory and anti-inflammatory cytokines in rats’ colonic tissues, including TNF-α, IFN-γ, IL-1β, IL-6, IL-10, IL-17A, IL-22, and IL-23." (PMID 39776580, 2024). "Interestingly, in the transfer of naïve T cells, IL‐22 from innate (NK/ILC) cells was suggested to next to the IL‐22 derived from CD4+ cells, also plays a protective role, since performing the transfer in Rag1−/−Il22−/− double KO mice resulted in exacerbated colitis." (PMID 38363052, 2024). "Whether the non-toxigenic strain Bacteroides fragilis depends on IL-22-mediated IL-10R2 activation to perform anti-inflammatory effects in colitis remains unclear." (PMID 37114045, 2023). "Additionally, to verify that IL‐22 plays an essential role in relieving the inflammatory response of colitis mice, IBD mice received intravenous injection of recombinant IL‐22 protein (rIL‐22) and anti‐IL‐22 antibody that neutralizes IL‐22 by blocking its expression (IL‐22 B)." (PMID 36404603, 2023). "Here, there also were differences in colon lengths and inflammatory cytokines in the KLPJ-infused IL22 KO mice compared with the uninfused IL22 KO mice, although this difference was less than those in WT with or without gavage, suggesting that IL22 also is partly involved in KLPJ-mediated colitis." (PMID 36436756, 2023). "In addition, Qing Dai and indigo may improve colitis by activating AHR to upregulate IL-10 and IL-22." (PMID 37179416, 2023). "The studies found that the development of ILC3 and the function of IL-22 secretion were significantly inhibited after the specific deletion of AHR in mice, allowing the expansion of commensal segment filamentous bacteria(SFB) to induce the Th17 cells-mediated colitis." (PMID 37122757, 2023). "AHR ligands, including TCDD, FICZ, and Norisoboldine (NOR), could ameliorate colitis symptoms by suppressing Th17 differentiation, leading to the increased IL-22 production, as well as decreased expression of IFN-γ and IL-17." (PMID 37942478, 2023). "Overexpression of IL-22 triggered by thymopentin could restore the composition of probiotics such as Lactobacillus and Akkermansia, normalizing the composition of the gut microbiome, suggesting IL-22 may alleviate DSS-induced colitis." (PMID 36135048, 2022). "TGFβ1 promotes amphiregulin production by intestinal epithelial cells, whereas IL22, which is produced in response to IL23 and TNFα, enhances the secretion of antimicrobial peptides such as S100A8/A9, resulting in the restoration of epithelial barrier function and the resolution of colitis." (PMID 35039631, 2022). "The decreased expression of proinflammatory cytokine and increased expression of anti-inflammatory cytokine were also observed in the miR-200b-3p- and miR-181b-5p-treated colitis groups, including IL-6, IL-1β and IL-10, but no significant changes in IL-22 was observed." (PMID 36176029, 2022). "Strikingly, these experiments revealed that TNF produced by epithelial cells can control epithelial cell repair, colonic TNF production and IL-22BP colonic levels, while myeloid cell derived TNF contributed to severity of colitis without influencing IL-22 levels in the colon." (PMID 35383266, 2022).
colitis (continued). "The other way around, IL-22bp-deficient rats recovered significantly faster from first signs of colitis upon DSS treatment compared to wildtype control animals, which could be traced back to the protective effects of efficient IL-22 signaling on the epithelial barrier." (PMID 33869257, 2021). "For example, lack of IL-22 in the IL-10–/– mice model prevents spontaneous colitis development." (PMID 34603258, 2021). "The IL-22–/– mice still developed more severe colitis upon DSS treatment than the wildtype mice when co-housed, and therefore both the lack of IL-22 function in the host, as well as the (‘transmissible’) microbiota of these mice play a role in the severity of DSS-induced colitis." (PMID 34603258, 2021). "Since it has been demonstrated that IL9-producing iNKT cells provide protective effects against DSS colitis in an IL4-dependent manner, we decided to examine whether this subset of iNKT cells cooperates with IL22-producing ILC3s in regulating colitis in Yeti mice." (PMID 33513946, 2021). "Lack of macrophage response to IL-10 results in the expression of several pro-inflammatory mediators and the development of colitis in mice: in particular, IL-23 secretion by IL-10Rα-negative macrophages induces IL-22 release by ILC3 and Th17 T cells, leading to the occurrence of colitis." (PMID 32650452, 2020). "Lack of IL-22 may account for insufficient intestinal mucus barrier repair and enhanced intestinal microfloral invasion during colitis, leading to the destruction of epithelial barrier integrity." (PMID 32391010, 2020). "Additionally, IL-22 was increased following treatment with I3C but not with butyrate, and neutralization of IL-22 blocked the beneficial effects of I3C against colitis." (PMID 33105907, 2020). "Since TRUC Il22−/− mice do not develop colonic epithelial ER stress and are protected from colitis, we hypothesised that direct induction of colonic epithelial ER stress, even in the absence of IL22, should be sufficient to reinstate disease." (PMID 31792136, 2020). "Furthermore, the absence of IL-22 completely prevented C. muridarum from alleviating colitis and significantly decreased the levels of occludin, an important downstream effector protein of IL-22." (PMID 33381598, 2020). "Nevertheless, our results indicate intDCs to be, at least partially, direct sources of IL-22 in response to different flagellins, which, in turn, might account for the observed distinct DSS-induced colitis phenotypes mediated by administration of different flagellins." (PMID 31206517, 2019). "TL1A promotes group 3 innate lymphoid cells to produce IL-22 which can protect acute colitis by promoting mucosal healing; furthermore, TL1A induces OX40L expression on group 3 innate lymphoid cells which stimulates T cell activation and is required for T cell-driven murine colitis." (PMID 31886308, 2019). "Both IL-22 and IL-18 have important roles in IEC proliferation and epithelial barrier repair; therefore, their decreased levels in Casp11−/− mice during DSS colitis are consistent with the increased barrier permeability and severe mucosal damage observed in these mice." (PMID 25548224, 2015). "Inhibition of IL-22 by neutralizing antibodies in wild type mice or the lack of IL-22 in KO mice with dextran-sodium-sulphate- (DSS-) induced colitis resulted in an increased inflammation and epithelial damage of the colon leading to more severe weight loss of the animals." (PMID 26199463, 2015). "In addition, DSS-induced colitis mice treated with TcES showed a significant increase in the production of IL-4 and the chemokine MCP-1 (CCL2), along with increased production of IL-22 and IL-31, both of which are cytokines involved in protecting the epithelial barrier." (PMID 40576745, 2025).
colitis (continued). "Given the role of IL-22 in epithelial protection and tissue homeostasis, along with the growing recognition of the influence of the gut microbiota in IBD, we hypothesize that IL-22 signaling may drive hemopexin upregulation as a protective mechanism in colitis." (PMID 40791589, 2025). "While it is possible that the increases in Il-17 and Il-22 expressions after RH supplementation are induced by the SCFA content, other active compounds in RH might also play a role in maintaining the integrity of the intestinal membrane against DSS-induced colitis." (PMID 39057682, 2024). "After DSS treatment, ILC3s primarily produce IL-22 rather than IL-17.28,67 Our data align with these findings, highlighting the beneficial roles of C. tropicalis induced IL-17A and IL-22 and the crosstalk between fungal intestinal colonization and host immune response in ameliorating colitis." (PMID 39462273, 2024). "Importantly, Ffar2 modulation did not affect lymphocytes of adaptive immunity, nor ILC1 or ILC2, but potentiated ILC3 proliferation and IL-22 production as the basis for the mechanism of action for the observed protective effect of Cpd1 against colitis and Citrobacter rodentium infection." (PMID 38238790, 2024). "Moreover, in Npm1+/− mice exposed to DSS, bezafibrate resulted in increased percentages of total colonic ILC3s, IL-22+ ILC3s and IL-22 production by ILC3s, suggesting that sufficient mitochondrial OXPHOS and biogenesis are required for ILC3 activity in DSS-induced colitis." (PMID 39103576, 2024). "Moreover, adding Indigo Naturalis to DSS-induced colitis mice can promote the expression of IL-10 and IL-22 in colonic lamina propria lymphocytes but not in AHR-deficient mice, which may be related to reduced production of regulatory cytokines." (PMID 37179416, 2023). "However, in mice exposed to DSS, the absence of IL-22 resulted in more severe colitis." (PMID 37179416, 2023). "Finally, genetic ablation of TNF in distinct cellular sources in this colitis model revealed that soluble TNF produced by IECs controls IL-22BP expression in the colon, while transmembrane T cell-derived TNF regulated inflammation and TNF production by IECs and, thereby, Il-22 bioactivity." (PMID 35383266, 2022). "Thus, the role of IL-22 in the context of chronic inflammation during IBD needs to be carefully re-evaluated, and the supplementation of exogenous IL-22, especially in an Fc fusion with long serum half-life, to patients with active colitis should be re-considered with extreme caution." (PMID 34992594, 2021). "However, since IL-36 is necessary for IL-22 production in DSS-induced colitis, it is not clear whether IL-36 differently regulates Th17 and Th22 differentiation in vivo among various animal models of gastrointestinal dysregulation." (PMID 34054828, 2021). "Indeed, double inactivation of both IL-10R and IL-23 in CX3CR1 macrophages (Il10raflox/floxIl23aflox/flox Cx3cr1-Cre mice) protected mice from colitis development, and moreover, Il10raflox/flox Cx3cr1-Cre mice lacking IL-22 (Il10raflox/flox Cx3cr1-Cre Il22−/− mice) did not develop colitis." (PMID 33562334, 2021). "However, we reasoned that if IL22 was biologically active in diseased colonic tissue of patients with colitis, then core IL22-responsive transcripts would be enriched in rectal biopsies of CD patients with active colitis in comparison with non-inflammatory control subjects." (PMID 31792136, 2020). "However, butyrate supplementation did not protect Il22−/− mice from DSS-induced colitis, although butyrate treatment in vivo increased both IL-22 and IL-10 production in mice, which suggests that butyrate induction of IL-10 alone is insufficient to decrease colitis severity in this model." (PMID 32901017, 2020).